TMEM276 (transmembrane protein 276)
Tractability: Antibody: UniProt predicts a signal peptide or a membrane-spanning region.
Gene: Protein-coding gene on chromosome 8 (144,463,817 to 144,466,890, reverse strand). Ensembl gene ENSG00000291317.
Subcellular location: Membrane
Gene Ontology:
Molecular function: protein binding
Cellular component: membrane
Homologues: Orthologues: mouse Tmem276 (88% identical), pig TMEM276 (85% identical), rat Tmem276 (71% identical), tropical clawed frog zftraf1 (38% identical).